MAGEC3 (MAGE family member C3)
Synonyms: CT7.2; HCA2; MAGE-C3; MAGEC4
Tractability: No criterion of Open Targets' tractability assessment is met for any kind of drug.
Gene: Protein-coding gene on chromosome X (141,838,316 to 141,897,832, forward strand). Ensembl gene ENSG00000165509.
Gene Ontology:
Biological process: negative regulation of transcription by RNA polymerase II
Cellular component: nucleus
Homologues: Orthologues: chimpanzee MAGEC3 (30% identical), rat Magea13 (15% identical), mouse Magea13 (14% identical), zebrafish ndnl2 (8% identical), Drosophila melanogaster MAGE (7% identical). Paralogues in human: MAGEC1 (30% identical), MAGEC2 (26% identical), MAGEA10 (23% identical), MAGEA8 (18% identical), MAGEA9 (17% identical), MAGEA9B (17% identical), MAGEB18 (17% identical), MAGEA1 (17% identical), MAGEA3 (17% identical), MAGEA6 (17% identical), MAGEB4 (16% identical), MAGEA11 (16% identical), and 25 more.
Diseases named in the same sentence as MAGEC3 in open-access papers:
MAGEC3 is named in the same sentence as 14 diseases in open-access papers, as found by Europe PMC text mining. Sharing a sentence is not in itself a finding about the gene and the disease. The quoted sentences say what the papers report.
ovarian carcinoma (4 papers, 2018 to 2024). A malignant neoplasm originating from the surface ovarian epithelium. "Like BRCA2, MAGEC3 is an ovarian cancer predisposition gene that has been shown to have prognostic significance in ovarian cancer patients." (PMID 36230652, 2022). "Given that ovarian cancers are highly immunogenic, we considered the association between MAGEC3 and the count of CD8+ tumor-infiltrating lymphocytes (TILs)." (PMID 35158998, 2022). "As there is a known association between MAGEC3 and prognosis in ovarian cancer, we stratified common primary disease sites of the TCGA cohort by MAGEC3 expression." (PMID 35158998, 2022). "In ovarian cancers with survival follow-up (n = 394), normal MAGEC3 levels were associated with complete response to maximal debulking surgery followed by platinum-based chemotherapy (CR mean 150.5 versus 138.9, two-sample t-test, p = 0.008)." (PMID 35158998, 2022). "Familial studies connect variants in the X-linked gene MAGEC3 to early-onset ovarian cancers." (PMID 35158998, 2022). "In an independent, model-building cohort and a further validation cohort, MAGEC3 was identified as a candidate prognostic biomarker associated with ovarian cancer with the potential for predictive marker-based treatment strategies based on targeting cases with high expression." (PMID 35158998, 2022). "They found by exome sequencing of 159 non-BRCA1/2 ovarian cancer cases that one missense variant (rs176026 in MAGEC3) was associated with risk at “chromosome-wide significance” (Hazard ratio [HR] = 2.85, 95% CI 1.75–4.65) and with a 6.7-year-earlier age of onset." (PMID 29958288, 2018). "Additional unpublished data from our lab revealed that ovarian cancer cells expressing MAGEC3 fare better under cisplatin (CDDP) insult by clearing cisplatin adducts." (PMID 36230652, 2022). "The inverse was seen for progression-free survival (PFS) in all women with epithelial ovarian cancer (normal MAGEC3: 16.2 months median versus 24.1 months, log-rank p = 0.002)." (PMID 35158998, 2022). "Like BRCA2, MAGEC3 protein expression has been identified for evaluation as a novel prognostic biomarker in ovarian cancer." (PMID 36230652, 2022). "We therefore sought to determine the relationship between MAGEC3 and BRCA2 expression in ovarian cancer and their association with patient characteristics and outcomes." (PMID 36230652, 2022). "While more work is required to assess its operating characteristics, higher relative MAGEC3 tumor protein was a significant biomarker for poor prognosis in ovarian cancer." (PMID 35158998, 2022). "This study aimed to evaluate BRCA2 and MAGEC3 for their influence on epithelial ovarian cancer progression and to assess the clinical significance of their combined expression." (PMID 36230652, 2022). "Ovarian cancer cases expressing BRCA2 with low levels of MAGEC3 fare better than those with normal levels." (PMID 36230652, 2022). "MAGEC3 protein was sporadically lost in ovarian cancers, with half of the cases falling below the 9.5th percentile of normal tissue expression." (PMID 35158998, 2022). "We quantified normal and tumor protein expression of MAGEC3 via immunohistochemistry in n = 394 advanced ovarian cancers, assessed the correlation of these values with clinicopathologic and immunological features and modeled survival using univariate and multivariate models." (PMID 35158998, 2022). "In this work, we measured MAGEC3 protein levels in ovarian cancers and normal tissues." (PMID 35158998, 2022). "The relationship between both BRCA2 and MAGEC3 protein expression and their combined clinical significance in ovarian carcinoma is unknown." (PMID 36230652, 2022). "Despite these limitations, our study used a large single-institution cohort of patients with definitive power to provide the first investigation of MAGEC3 protein expression in ovarian cancer cases and to confirm the gene’s relevance to cancer biology and patient prognosis." (PMID 35158998, 2022).
ovarian carcinoma (continued). "However, the relationship between both BRCA2 and MAGEC3 protein expression and their combined clinical significance in ovarian carcinoma is unknown." (PMID 36230652, 2022). "For ovarian cancer patients with optimal cytoreduction, combined expression of MAGEC3 and BRCA2 showed that patients that were BRCA2 expressors with MAGEC3 loss levels had better overall and progression-free survival compared with patients who were BRCA2 expressors with normal MAGEC3 levels." (PMID 36230652, 2022). "Previously, we described a linkage between early-onset ovarian cancers and MAGEC3 and more recently found that MAGEC3 is a potential prognostic biomarker in ovarian cancer, as loss levels were associated with a favorable progression-free survival (PFS) in ovarian cancer patients." (PMID 36230652, 2022). "Despite these limitations, our study has considerable strengths, including the analysis of a large cohort of patients to provide insight into the relationship between MAGEC3 and BRCA2 protein expression in ovarian cancer cases." (PMID 36230652, 2022). "We found a weak inverse correlation between MAGEC3 and BRCA2 expression in epithelial ovarian cancers." (PMID 36230652, 2022). "The aim of this study was to evaluate the role of MAGEC3 and BRCA2 in epithelial ovarian cancer progression." (PMID 36230652, 2022). "We applied the MAGEC3 protein level predictor to an independent set of cases sequenced and processed for TCGA’s pan-cancer analysis (n = 282 ovarian cancer patients), which did not have measured MAGEC3 protein levels." (PMID 35158998, 2022). "In this retrospective cohort study, we determined that, unlike other MAGE family members, the MAGEC3 protein is normally expressed in ovarian tissue but is lost in half of the ovarian cancers." (PMID 35158998, 2022). "Preliminary in vitro data from our lab supports this hypothesis, as overexpression of MAGEC3 results in a reduction in BRCA2 protein level in both fibrosarcoma (HT1080) and ovarian cancer (SKOV3) cell lines." (PMID 36230652, 2022). "Consistent with the supposition that it is a tumor suppressor, MAGEC3 levels were lower on average in ovarian cancers than in normal ovary tissue." (PMID 35158998, 2022). "Rare variants in MAGEC3 are associated with BRCA negative, early-onset ovarian cancers." (PMID 35158998, 2022).
ovarian tumor (2 papers, 2022). "CD8+ TIL levels were positively correlated with MAGEC3 expression in ovarian tumors (Pearson’s r = 0.176, p = 0.011)." (PMID 35158998, 2022).
autism (1 paper, 2024). Persistent deficits in social interaction and communication and interaction as well as a markedly restricted repertoire of activity and interest as well as repetitive patterns of behavior. "First, they identified risk-enriched regions (RERs) using microarray data, and then they used whole-exome sequencing data to explore the rare maternally-inherited damaging variants in autism followed by transmission disequilibrium test which pointed to novel autism risk gene, MAGEC3." (PMID 39296887, 2024).
breast carcinoma (1 paper, 2022). "Other reports studying MAGEC3 mRNA (using Affymetrix oligonucleotide arrays, probe 216592_at) show associations with positive prognosis in hepatocellular carcinoma and mixed relapse-free survival based on lymph node status in breast cancer." (PMID 35158998, 2022).
hepatocellular carcinoma (1 paper, 2022). A malignant tumor that arises from hepatocytes. "This would also explain why MAGEC3 shows an opposite correlation with survival in hepatocellular carcinoma, which is not predominantly treated with platinum." (PMID 35158998, 2022).
melanoma (1 paper, 2020). A malignant, usually aggressive tumor composed of atypical, neoplastic melanocytes. "The six pan-cancer X-linked genes (ATRX, CNKSR2, DDX3X, KDM5C, KDM6A, and MAGEC3) were examined for their association with melanoma survival by comparing the survival of all patients with the expression of genes above (high) or below (low) median expression levels." (PMID 32731355, 2020).
cancer (8 papers, 2015 to 2025). A tumor composed of atypical neoplastic, often pleomorphic cells that invade other tissues. "To extend these results, we quantified MAGEC3 protein expression in n = 180 cancers and used matching RNA sequencing data to determine MAGEC3-associated differentially expressed genes and to build an RNA-based model of MAGEC3 protein levels." (PMID 35158998, 2022). "Recently, computational modeling of sex-bias in cancers affecting both sexes has identified MAGEC3 directly as a putative X-linked tumor suppressor." (PMID 29447163, 2018). "While MAGEC3 is thought to be a cancer testis antigen, it shows some expression in normal heart, brain, fallopian tube and pituitary gland tissues suggesting that the loss of expression of MAGEC3 plays some role in cancer formation." (PMID 29447163, 2018). "It has been confirmed that MAGEC3 can stimulate cancer metastasis via intriguing epithelial-mesenchymal and immunosuppression in ESCC." (PMID 37313409, 2023). "These patterns are consistent with the idea that MAGEC3 may perform a tumor suppressive function like many inherited cancer genes." (PMID 29447163, 2018). "MAGEC3 also upregulates a stress-related gene, WRNIP1, a DNA replication gene, MCM7, and cancer-related genes, XPO5 and ZSCAN16." (PMID 35158998, 2022). "Unlike other cancer-testis antigens, which are expected to have no expression in normal tissue, MAGEC3 appears to have low to moderate expression in a range of normal tissues tested by the GTEx project." (PMID 29447163, 2018). "Notably in the cancers, there were three groups present: the set around the unity line where MAGEC3 expression was at the limit of detection, a set left of the line (7.1% 23/306) where MAGEA1 is likely expressed, a set right of the line (12.4%, 38/306) where MAGEC3 may be expressed." (PMID 29447163, 2018).
tumor (8 papers, 2018 to 2024). "It proved to be a viable and cost-effective approach for determining BRCA2 protein expression in tumor samples for this study, as similarly reported by other studies, as well as for determining MAGEC3 protein expression." (PMID 36230652, 2022). "One study has shown that six of such genes show increased loss-of-function mutations in male tumor diseases (ATRX, CNKSR2, DDX3X, KDM5C, KDM6A, and MAGEC3)." (PMID 32629877, 2020). "In addition, MAGEC3 downregulates genes that are shown to induce tumor progression, including APLMR, FBLN5, and FNDC1." (PMID 35158998, 2022). "MAGEC3 protein was correlated with CD8 protein expression [Pearson’s r = 0.176, p = 0.011], NY-ESO-1 seropositivity, and mRNA expression of tumor antigens at Xq28." (PMID 35158998, 2022). "In contrast, those cases with higher MAGEC3 expression and poor prognosis likely reflect a MAGE-independent form of the disease (and not a pro-tumor function for MAGEC3) because the level of tumor expression is not significantly increased above normal tissue." (PMID 35158998, 2022). "Stratified at the median of tumor expression (corresponding to the 9.5th percentile of normal ovary expression), higher levels of MAGEC3 were not different from the normal ovary (t-test p = 0.368), while lower levels of MAGEC3 were significantly lower (p < 0.001), reflecting loss of expression." (PMID 35158998, 2022). "Our analysis identified high expression of MAGEB2, MAGEC3, and MAGEB17 only in the non-viral-infected tumor group, in which we observed the overexpression of genes involved in stress response." (PMID 36557005, 2022).
MAGEC3 also shares sentences with these, for which no sentence is quoted: glioblastoma (1 paper); head and neck squamous cell carcinoma (1); hereditary cancer (1); Onset (1); prostate carcinoma (1); Thyroid Carcinoma (1).